ANAPC7 (anaphase promoting complex subunit 7)
Description:
Component of the anaphase promoting complex/cyclosome (APC/C), a cell cycle-regulated E3 ubiquitin ligase that controls progression through the cell cycle. APC/C acts by mediating ubiquitination and subsequent degradation of target proteins: it mainly mediates the formation of 'Lys-11'-linked polyubiquitin chains and, to a lower extent, the formation of 'Lys-48'- and 'Lys-63'-linked polyubiquitin chains. APC/C catalyzes assembly of branched 'Lys-11'-/'Lys-48'-linked branched ubiquitin chains on target proteins. APC/C is activated by CDC20 in the metaphase/anaphase transition of cell cycle, targeting the degradation of cyclin B and securin. APC/C is regulated by the mitotic checkpoint complex (MCC), which inhibits APC/C and delays chromosome segregation. Has an enzyme-substrate adapter activity mediating the processive ubiquitination of specific substrates. Involved in brain development through the specific ubiquitination and clearance of MKI67 from constitutive heterochromatin after neuronal progenitors exit mitosis.
Synonyms: APC7; FERBON
Tractability: PROTAC: ubiquitination databases record sites on it; its protein half-life has been measured.
Gene: Protein-coding gene on chromosome 12 (110,372,900 to 110,403,730, reverse strand). Ensembl gene ENSG00000196510.
Subcellular location: Cytoplasm, cytoskeleton; Nucleus; Cytoplasm, cytoskeleton, spindle
Subcellular location (Human Protein Atlas): Cytokinetic bridge; Microtubules; Mitotic spindle; Nucleoplasm; Vesicles
Pathways (Reactome):
Cell Cycle: APC-Cdc20 mediated degradation of Nek2A; APC/C:Cdc20 mediated degradation of Cyclin B; APC/C:Cdc20 mediated degradation of Securin; APC/C:Cdc20 mediated degradation of mitotic proteins; APC/C:Cdh1 mediated degradation of Cdc20 and other APC/C:Cdh1 targeted proteins in late mitosis/early G1; Autodegradation of Cdh1 by Cdh1:APC/C; Cdc20:Phospho-APC/C mediated degradation of Cyclin A; Conversion from APC/C:Cdc20 to APC/C:Cdh1 in late anaphase; Inactivation of APC/C via direct inhibition of the APC/C complex; Phosphorylation of the APC/C; Regulation of APC/C activators between G1/S and early anaphase; Separation of Sister Chromatids
DNA Replication: Assembly of the pre-replicative complex; CDK-mediated phosphorylation and removal of Cdc6
Cellular responses to stimuli: Senescence-Associated Secretory Phenotype (SASP)
Disease: Aberrant regulation of mitotic exit in cancer due to RB1 defects
Gene expression (Transcription): Transcriptional Regulation by VENTX
Immune System: Antigen processing: Ubiquitination & Proteasome degradation
Gene Ontology:
Molecular function: enzyme-substrate adaptor activity; protein phosphatase binding
Biological process: anaphase-promoting complex-dependent catabolic process; brain development; protein branched polyubiquitination; protein K11-linked ubiquitination; protein K48-linked ubiquitination; protein ubiquitination; cell division; positive regulation of mitotic metaphase/anaphase transition; regulation of meiotic cell cycle; regulation of mitotic cell cycle
Cellular component: anaphase-promoting complex; heterochromatin; intercellular bridge; microtubule cytoskeleton; mitotic spindle; nucleus; spindle; cytosol; nucleoplasm; cytoskeleton
Genetic constraint (gnomAD): Loss-of-function variants: 20 observed, 60.84 expected, observed/expected ratio (o/e) 0.33, 90% interval 0.23 to 0.48. The upper end of that interval is the gene's LOEUF score, 0.48, which puts it in group 2 of 6, group 1 being the genes least tolerant of losing a copy. Missense variants: 505 observed, 709.89 expected, observed/expected ratio (o/e) 0.71, 90% interval 0.66 to 0.77. Synonymous variants: 239 observed, 260.56 expected, observed/expected ratio (o/e) 0.92, 90% interval 0.82 to 1.02.
Homologues: Orthologues: chimpanzee ANAPC7 (99% identical), dog ANAPC7 (99% identical), macaque ANAPC7 (99% identical), pig ANAPC7 (99% identical), rabbit ANAPC7 (99% identical), rat Anapc7 (98% identical), mouse Anapc7 (98% identical), tropical clawed frog anapc7 (94% identical), guinea pig ANAPC7 (94% identical), zebrafish anapc7 (89% identical), Drosophila melanogaster APC7 (27% identical). Paralogues in human: CDC27 (18% identical), CDC16 (17% identical), CDC23 (15% identical).
Diseases named in the same sentence as ANAPC7 in open-access papers:
ANAPC7 is named in the same sentence as 9 diseases in open-access papers, as found by Europe PMC text mining. Sharing a sentence is not in itself a finding about the gene and the disease. The quoted sentences say what the papers report.
acute myeloid leukemia (2 papers, 2018 to 2023). Acute myeloid leukemia (AML) is a group of neoplasms arising from precursor cells committed to the myeloid cell-line differentiation. "As a vital part of APC, ANAPC7 dysregulation contributes to the development of cancers such as acute myeloid leukemia." (PMID 36592213, 2023).
breast carcinoma (2 papers, 2020 to 2023). "A study on breast cancer revealed that ANAPC7 expression was elevated, which corresponds to a more malignant tumor condition." (PMID 36592213, 2023). "Considering the vital function of APC/C in eukaryotic cells mitosis, ANAPC7 might play an essential role in fulvestrant resistance, and ANAPC7 (anaphase-promoting complex subunit 7) was expected to be a novel biomarker or therapeutic target for fulvestrant-resistant breast cancer." (PMID 33133141, 2020). "In our study, high expression of ANAPC7 was correlated with significantly worse RFS in the specific cohort of breast cancer patients, and the expression level of ANAPC7 was continuously high in the fulvestrant-resistant breast cancer cells." (PMID 33133141, 2020).
intellectual disability syndrome (2 papers, 2023 to 2024). "Studies have shown that the loss of ANAPC7 is associated with intellectual disability syndrome, which may also explain the intellectual disability in toddlers with ASD." (PMID 37528852, 2023). "Homozygous ANAPC7 mutations in humans, leading to loss of APC7 protein, underlies an inherited intellectual disability syndrome, caused by defective APC/CΔAPC7-mediated degradation of the chromosome-associated protein Ki-67." (PMID 39401078, 2024).
diabetes (1 paper, 2013). "Three candidates had potential roles in biochemical and/or immune signaling and hence were pursued in this study: Ras-related associated with diabetes (Rrad), complement factor D (CFD, also known as adipsin) and anaphase promoting complex subunit 7 (AnapC7)." (PMID 23922952, 2013).
kidney disease (1 paper, 2025). "To validate the potential genes is functionally in kidney disease, we choose whole genes (CDC16, CDC20, CDC27, MAD2L1, ANAPC1, ANAPC7, BUB1B) from first highest score subnetwork obtained from Cytoscape MCODE plugin from upregulated genes PPI as hub genes." (PMID 40034749, 2025).
ANAPC7 also shares sentences with these, for which no sentence is quoted: cancer (4 papers); tumor (2); asthma (1); Intellectual disability (1).